HLA-DRB9 (major histocompatibility complex, class II, DR beta 9 (pseudogene))
Synonyms: D6S206; D6S206E; formerly HLA-DRB1L; HLA-DR1BL
Gene: Transcribed unprocessed pseudogene on chromosome 6 (32,459,821 to 32,473,500, reverse strand). Ensembl gene ENSG00000196301.
Diseases named in the same sentence as HLA-DRB9 in open-access papers:
HLA-DRB9 is named in the same sentence as 6 diseases in open-access papers, as found by Europe PMC text mining. Sharing a sentence is not in itself a finding about the gene and the disease. The quoted sentences say what the papers report.
rheumatoid arthritis (2 papers, 2021 to 2023). A chronic, systemic autoimmune disorder characterized by inflammation in the synovial membranes and articular surfaces. "Interestingly, the rs1964995 SNP located between HLA-DRB9 and HLA-DRB5, a risk SNP only in AAs in our study, was protective in a Swedish cohort with non-Lofgren sarcoidosis GWAS, but increased the risk of rheumatoid arthritis in ADs, but not in EDs." (PMID 38390497, 2023).
asthma (1 paper, 2025). "Interestingly, certain HLA gene variants such as HLA-DQA1, HLA-DQB1, and HLA-DRB9 are also associated with asthma." (PMID 40661126, 2025).
lung carcinoma (1 paper, 2021). "Currently, there is no definitive study on the relationship between HLA-DRB9, HLA-DQB2 and lung cancer, and further verification will be needed." (PMID 34938740, 2021).
sarcoidosis (1 paper, 2023). Sarcoidosis is a multisystemic disorder of unknown cause characterized by the formation of immune granulomas in involved organs. "This same study identified HLA-DRB9 and HLA-DRB5 as associated with sarcoidosis risk." (PMID 38390497, 2023).
HLA-DRB9 also shares sentences with these, for which no sentence is quoted: hyperthyroidism (1 paper); sarcopenia (1).